INS (insulin)
Diseases named in the same sentence as INS in open-access papers (continued):
Sharing a sentence is not in itself a finding about the gene and the disease.
Hypoglycemia (continued). "Moreover, they noted that individuals with an enhanced insulin response to the pre-exercise meal tended to be more prone to transient hypoglycemia in the fasted state." (PMID 32982972, 2020). "To date, several studies have shown that metformin therapy has greater benefits compared with insulin and glibenclamide as GDM treatments, such as lower risk of large for gestational age babies or macrosomia, neonatal hypoglycemia, and admission to neonatal intensive care units." (PMID 32625081, 2020). "Treatment of hypoglycemia due to insulin secreting tumours has two parts." (PMID 34394252, 2020). "Investigations performed after an overnight fast revealed a morning serum glucose level of 1.9 mmol/L, insulin level of 141 pmol/L (normal range, less than 20.8 pmol/L [3 mU/L] during hypoglycemia), and C-peptide level of 1106 pmol/L (normal reference range, 260–1730 pmol/L)." (PMID 32605595, 2020). "Hence, in patients with anemia, hypoglycemia can go undetected due to false high glucose values and can lead to the administration of incorrect insulin dosages." (PMID 32430994, 2020). "However, it rapidly declined after insulin administration suggesting it is consumed by the brain during hypoglycemia." (PMID 33173467, 2020). "In ketoacidotic patients, accurate and frequent glucose monitoring is the best way to avoid a rapid decrease in the BG concentration, which could result in cerebral edema and hypoglycemia, and to allow correct management of insulin treatment." (PMID 31725202, 2020). "With the sensitive assay, the diagnosis of CHI could be made exclusively based on p-insulin above cut-off during hypoglycemia in our data set." (PMID 33679602, 2020). "With regard to glycemic control, it was also similar when comparing both groups with regard to mean capillary blood glucose, insulin dose, and glycemic variability; however, we observed a small but significantly higher number of mild hypoglycemia events in the n-3 PUFA group." (PMID 32471262, 2020). "Because insulin and insulin-secreting drugs may induce hypoglycemia which would lead to AF, residual confounding from other antidiabetic drugs could not be excluded." (PMID 33693008, 2020). "Beyond hypoglycemia, insulin exerts sympathoactivatory and parasympathoinhibitory actions." (PMID 33292431, 2020). "Importantly, male patients had a significantly increased incidence of hypoglycemia during intensive insulin therapy." (PMID 32090123, 2020). "Given the ability of insulin-induced hypoglycemia to trigger cognitive deficits selectively in mice with existing neurodegenerative disease (ME7), we examined whether LPS produced differential hypoglycemic responses in NBH and ME7 animals." (PMID 32513828, 2020). "A recent study demonstrated that random non-fasting C-peptide levels can be used to indicate hypoglycemia risk in insulin-treated T2DM individuals." (PMID 33023555, 2020). "GHRH activation was greater with 2DG than with insulin hypoglycemia." (PMID 33148883, 2020). "No increased risk was found for cardiovascular events and hypoglycemia; however, an increased risk of all-cause mortality was observed in patients receiving basal insulin." (PMID 32238842, 2020). "Fear of hypoglycemia promotes dysfunctional behaviors in order to prevent hypoglycemia such as maintaining high blood glucose levels by limiting physical activity, reducing the required insulin dose, and increasing carbohydrate intake." (PMID 32771061, 2020). "The analysis showed that rates of severe hypoglycaemia were approximately 50% lower with Gla-300 versus insulin glargine 100 U/mL or insulin detemir in insulin-naïve individuals, and 30% lower versus insulin detemir in patients switched from basal insulin." (PMID 32337298, 2020). "Hypoglycemia occurrence and adverse reactions also might be related to the pen injector and the insulin itself." (PMID 33086494, 2020).
Hypoglycemia (continued). "Poor recognition of hypoglycaemia, travelling, optimisation of body weight and/or menstrual cycle variations in insulin sensitivity are a few factors that may have an impact on glucose control and performance." (PMID 32533229, 2020). "When counseling patients, it is essential to emphasize the importance of self-monitoring blood glucose and instruct patients how to down-titrate insulin to avoid hypoglycemia (i.e., reducing or eliminating bolus insulin if limiting caloric intake or skipping meals)." (PMID 33292727, 2020). "The accumulation of insulin in the body may induce severe hypoglycemia, which may lead to pituitary apoplexy and even be fatal." (PMID 32328036, 2020). "Serum insulin concentrations during hypoglycemia were 41 U/μL (reference range, 10-29 U/μL)." (PMID 32592436, 2020). "Potential underlying mechanisms are unclear, but the variability in HbA1c could result in a poor response to insulin therapy or hypoglycemia." (PMID 32973680, 2020). "For those with T1D, the fear of hypoglycaemia around exercise prevails as the main barrier to regular engagement, whilst a greater knowledge of insulin pharmacokinetics and/or using appropriate approaches to minimize exercise-related hypoglycaemia are associated with fewer perceived hurdles." (PMID 33495732, 2020). "Indeed, hypoglycemia is one of the main adverse effects of insulin therapy, as well as of oral antidiabetics, especially sulfonylureas and meglitinides." (PMID 32722515, 2020). "Continuous glucose monitoring (CGM) in combination with rapid-acting insulin analogs have improved glucose control, reducing hypoglycemia and episodes of diabetic ketoacidosis (DKA), resulting in more time spent in optimum glucose levels compared to standard monitoring." (PMID 33332410, 2020). "Xylitol ingestion in dogs is potentially lethal, stimulating insulin secretion, and causing marked hypoglycaemia, although this has never been reported in cats." (PMID 32500084, 2020). "As glucagon is a counterregulatory hormone, we also explored whether glucagon was inappropriately secreted in HFD-fed mice during insulin-induced hypoglycaemia in response to an insulin tolerance test (ITT)." (PMID 32446876, 2020). "Important precipitating factors of severe hypoglycemia in older adults are the decline in food intake along with an unchanged dose of SU drugs or the administration of the wrong insulin product, and inappropriate diet or dietary timing, excessive alcohol intake, and sick days." (PMID 33139628, 2020). "DA and L-DOPA derived from nutritional tyrosine may serve to defend against hypoglycemia via inhibition of glucose-stimulated β-cell insulin secretion as proposed by the anti-incretin hypothesis." (PMID 30876866, 2019). "Beta blocker use is associated with increased odds of hypoglycemia among hospitalized patients not requiring basal insulin, and odds are greater for selective beta blockers than for carvedilol." (PMID 31775749, 2019). "Degludec could be of particular benefit to those patients suffering recurrent hypoglycaemia and those who require additional flexibility in the dosing of insulin." (PMID 31796048, 2019). "Diazoxide can inhibit secretion of insulin and ease the condition of hypoglycemia." (PMID 29166433, 2019). "Previous work has shown that postprandial exercise is associated with an increased risk of hypoglycemia if the pre-meal insulin dose is not reduced." (PMID 31428047, 2019). "When stimulating insulin secretion at low glucose levels, they seem to promote hypoglycemia." (PMID 31658729, 2019). "Furthermore, integrated insulin pump and CGM systems are now increasingly available; this has improved the ease of insulin delivery in addition to prevention of severe hypoglycemia, one of the most feared complications of treatment with insulin." (PMID 30875898, 2019).
Hypoglycemia (continued). "Further, there was a greater odds of hypoglycemia associated with SBB vs. carvedilol in basal insulin non-users (OR 1.38, 95% CI 1.02–1.86, p = 0.03) but not in users (OR 0.84, 95% CI 0.52–1.36, p = 0.47)." (PMID 31775749, 2019). "For example, patients may develop a fear of hypoglycemia, which could manifest in omitting or decreasing insulin in an attempt to avoid hypoglycemia." (PMID 31138204, 2019). "The incremental costs with degludec were caused by increased cost of insulin which were partially offset by lower costs of non-severe hypoglycaemia." (PMID 31796048, 2019). "However, he reported multiple episodes of hypoglycemia after starting ivacaftor, prompting cessation of insulin therapy." (PMID 31010313, 2019). "However, participants in the study by Mattsson, Jendle and Adolfsson spent ~10% of their time in hypoglycemia, suggesting that adaptation of insulin was still challenging." (PMID 31835538, 2019). "Glucagon, a biologically active peptide, is known to be effective for the treatment of insulin-induced hypoglycemia and may be used to maintain the normal circulating glucose level in patients with pancreatectomy." (PMID 31052466, 2019). "Thus, patients whose HbA1c is lowered with the combination of sotagliflozin and insulin are less likely to experience hypoglycemia than those whose HbA1c reductions of a similar magnitude are achieved with insulin intensification alone." (PMID 31335194, 2019). "The higher magnitude of hypoglycemia in this study might be due to fact that most of the diabetic patients had type 1diabetes and were on insulin." (PMID 30700277, 2019). "When hypoglycemia occurred in our patient, both serum C-peptide and insulin levels increased." (PMID 29166433, 2019). "The alleviated oxidative stress might contribute to the hypoglycemia and insulin-sensitizing effects of FA-90F." (PMID 31340583, 2019). "This insulin-independent mechanism decreases blood pressure, individual weight and plasma glucose levels without causing hypoglycemia." (PMID 31658729, 2019). "The carbohydrate requirement to prevent exercise-mediated hypoglycemia increases with plasma insulin levels, with the pattern of blood glucose response to exercise being highly unpredictable under hyperinsulinaemic compared to near basal insulinaemic conditions." (PMID 31258513, 2019). "Unless the patient is using a sulfonylurea or insulin, the risk of hypoglycemia is low and no additional glucose monitoring would be routinely recommended during fasting." (PMID 31003482, 2019). "In these situations, individuals with T1D may opt to correct their blood glucose with an insulin bolus after exercise; however, care must be taken to avoid overcorrecting, as this can lead to severe post-exercise or nocturnal hypoglycemia." (PMID 31835538, 2019). "Continuous subcutaneous insulin infusion and continuous glucose monitoring have both been found to improve glycemic control without worsening hypoglycemia occurrence: Indeed, CSII has been associated with lower rates of (nocturnal) hypoglycemia." (PMID 30696060, 2019). "In this systematic review and meta-analysis we originally report clinical evidence on therapeutical use of short-acting insulin analogues compared with regular insulin while focusing on the main benefits of these analogues, namely the reduction of hypoglycemia and postprandial glucose levels." (PMID 30622653, 2019). "Muscle Bmal1-deletion caused glucose intolerance and hypoglycemia in the non-fasting state, and led to muscle-specific damage in insulin-stimulated glucose uptake." (PMID 31851682, 2019). "According to Taborsky's group, this loss of sympathetic innervation may partly explain the impaired glucagon response to insulin-induced hypoglycemia during T1DM." (PMID 31620088, 2019). "On the other hand, an over dosing of insulin can cause hypoglycemia (BG < 70 mg/dl) that, if severe and not promptly treated, can be catastrophic, causing loss of consciousness, seizures and even death." (PMID 30922295, 2019).
Hypoglycemia (continued). "The most novel aspect of the two new models introduced within this work is that they both seek to describe the dynamics between glucose, insulin and glucagon, given that the relationship between glucose and glucagon is key when a patient experiences hypoglycemia." (PMID 31829209, 2019). "One of the two users of insulin mixture developed severe hypoglycemia." (PMID 30815039, 2019). "However, one study in Ethiopia reported that insulin was the main reason for almost 70% of the occurrence of hypoglycemia that is higher than the result of this study." (PMID 31093506, 2019). "In particular, the incidence of neonatal hypoglycemia was increased in neonates delivered by mothers who had received isoxsuprine, while increased blood insulin and decreased blood glucose were found in neonates delivered by mothers who had received fenoterol or terbutaline." (PMID 31019720, 2019). "However, there are some concerns regarding a higher risk of macrosomia, large-for-gestational age infants, and neonatal hypoglycemia compared to insulin." (PMID 31781670, 2019). "This may result in poor adherence to therapy, leading to hyperglycaemia, while on the other hand, those injecting insulin could suffer from nocturnal hypoglycaemia." (PMID 30658518, 2019). "Improved glycaemic control was achieved without increasing the risk of hypoglycaemia and without an increase in total daily insulin dose." (PMID 30935872, 2019). "Thus, the subjects with history of severe hypoglycemia due to overdose of insulin or sulfonylureas were also excluded." (PMID 31296192, 2019). "The HypoDeg trial is designed to investigate whether insulin degludec in comparison with insulin glargine U100 is superior in limiting the occurrence of nocturnal hypoglycaemia in patients with recurrent nocturnal severe hypoglycaemia." (PMID 31337371, 2019). "Insulin was injected on day 3 only in the single-hypoglycemia group." (PMID 31013147, 2019). "Guidelines recommend consuming 10 to 15 g of carbohydrate to prevent exercise-induced hypoglycemia, but many studies illustrate that carbohydrate supplementations must be individualized to the type of insulin, i.e., peak insulin levels and duration of insulin action, as well as the absorptive state." (PMID 31611821, 2019). "Asian people with T2DM face the risk of hypoglycaemia, weight gain, difficulties in reducing PPG, and the complexities of subcutaneous injection, dose titration, and regular self‐monitoring of blood glucose associated with basal insulin therapy." (PMID 31050109, 2019). "In addition, one previous report stated that the rate of hypoglycemia among insulin users tended to increase along with increasing variations in blood glucose level." (PMID 30815039, 2019). "Pancreatic β-cells decrease insulin secretion during fasting to prevent hypoglycemia." (PMID 30683850, 2019). "Insulin levels were unchanged in KO relative to WT pups, suggesting that their hypoglycemia may alternatively have arisen through impaired gluconeogenesis and/or increased glycolytic flux." (PMID 31324765, 2019). "As continuous intravenous insulin therapy is generally necessary and potentially serious complications can appear during therapeutic management (hypokalemia, hypoglycemia, pulmonary edema, cerebral edema), close clinical and paraclinical monitoring is indispensable." (PMID 31418093, 2019). "It is anticipated that the impact of the PIC (e.g. time to FDG injection, need for repeat injections, incidence of hypoglycaemia) may be greater at other departments with less experience in pre-FDG insulin administration." (PMID 30737563, 2019). "However, in the group receiving intravenous insulin, eight participants experienced episodes of severe hypoglycemia (defined as blood glucose < 2.2 mM), versus only one participant in the subcutaneous group (p = 0.010)." (PMID 31261760, 2019).
Hypoglycemia (continued). "If fitness is the goal, and the patient has a plan to incrementally increase physical activity over time, it will be important to anticipate a reduction in total daily insulin requirement to avoid hypoglycemia as insulin sensitivity increases in response to exercise training." (PMID 31258513, 2019). "However, other studies suggest brain glycogen content is increased following recovery from insulin-induced hypoglycaemia and following recurrent 2-deoxyglucose-induced glucoprivation (reduction in utilisable glucose) in mice." (PMID 30293112, 2019). "A reduction in doses of insulin or SUs may be necessary when co-administered with a SGLT2i to prevent hypoglycemia." (PMID 31426529, 2019). "Ablation of these VMH SF1 neurons impairs the recovery from insulin-induced hypoglycemia, while their activation, under normoglycemic conditions, raises blood glucose levels by increasing glucagon secretion and inhibiting glucose-stimulated insulin secretion." (PMID 31072002, 2019). "The system automatically suspends basal insulin delivery when glucose concentration is predicted to reach or fall below a preset glucose threshold in the next 30 min and automatically restarts basal insulin on recovery from hypoglycemia." (PMID 30922295, 2019). "The most prominent hypoglycemia inducers are sulfonylureas and insulin therapy." (PMID 31772942, 2019). "In addition to being affected by insulin levels, the amount of carbohydrate to prevent exercise mediated hypoglycemia varies with the intensity and duration of exercise." (PMID 31258513, 2019). "In a recent study of pediatric patients with T1DM, patients with insulin pump therapy were shown to have lower rates of severe hypoglycemia, lower incidence of diabetic ketoacidosis, lower HbA1c, and lower total daily insulin doses than matched patients on multiple daily insulin injection therapy." (PMID 30875898, 2019). "Overly aggressive antidiabetic therapy may lead to hypoglycemia, and both insulin, as well as thiazolidinediones, can lead to fluid retention and worsening of HF." (PMID 31189473, 2019). "In light of this hypothesis, the strong and long-lasting increase in hypothalamic insulin signaling in HFD offspring at P21 might be one reason for the observed activation of microglia in order to prevent potential hypoglycemia." (PMID 31572115, 2019). "The results also suggest that fenofibrate might be beneficial in preventing hypoglycaemia, as fenofibrate-treated mice had an improved response to insulin-induced hypoglycaemia." (PMID 31410530, 2019). "Larger studies on populations undergoing hemodialysis will be required to determine whether our outcomes should be used for insulin adjustment on dialysis days to optimize glycemic control and avoid hypoglycemia." (PMID 31828166, 2019). "For instance, whole-body inactivation of brain and muscle ARNT-like 1 (Bmal1) or circadian locomotor output cycles kaput (Clock) could suppress glucose rhythm, impair gluconeogenesis, and inhibit glucose recovery in insulin-induced hypoglycemia." (PMID 31851682, 2019). "This implies that the ensemble approach has better generalization capabilities compared to other models on predictions of the occurrence of postprandial hypoglycemia during various glycemic changes which are affected by carbohydrate in a meal and injected insulin doses." (PMID 31694629, 2019). "Furthermore, it is well-known that insulin pump therapy is a treatment option for those patients with recurrent episodes of severe hypoglycaemia." (PMID 30889868, 2019). "The incidence of hypoglycemia with SGLT2i overall tends to be similar to that with placebo or non- SGLT2i antidiabetic drugs, such as metformin, glitazones and DDP4i, and lower when compared with insulin or SUs." (PMID 31426529, 2019). "In this scenario, a glutamate-driven increase in DMV neuron activity might result in increased insulin release, which would be consistent with the hypoglycemia reported after vagal efferent stimulation." (PMID 30804396, 2019).